RHOV (ras homolog family member V)
Description:
Plays a role in the control of the actin cytoskeleton via activation of the JNK pathway.
Synonyms: ARHV; WRCH2; Chp
Tractability: Antibody: its Gene Ontology location is reachable by antibodies, with high confidence; UniProt places it where antibodies can reach, with medium confidence. PROTAC: ubiquitination databases record sites on it.
Gene: Protein-coding gene on chromosome 15 (40,872,214 to 40,874,234, reverse strand). Ensembl gene ENSG00000104140.
Subcellular location: Cell membrane; Endosome membrane
Pathways (Reactome):
Signal Transduction: RHOV GTPase cycle
Gene Ontology:
Molecular function: protein binding; protein kinase binding; G protein activity; GTP binding; GTPase activity
Biological process: actin filament organization; endocytosis; establishment of cell polarity; small GTPase-mediated signal transduction
Cellular component: endosome membrane; plasma membrane
Genetic constraint (gnomAD): Loss-of-function variants: 4 observed, 18.43 expected, observed/expected ratio (o/e) 0.22, 90% interval 0.11 to 0.5. The upper end of that interval is the gene's LOEUF score, 0.5, which puts it in group 2 of 6, group 1 being the genes least tolerant of losing a copy. Missense variants: 249 observed, 288.48 expected, observed/expected ratio (o/e) 0.86, 90% interval 0.78 to 0.96. Synonymous variants: 127 observed, 122.61 expected, observed/expected ratio (o/e) 1.04, 90% interval 0.9 to 1.2.
Homologues: Orthologues: chimpanzee RHOV (100% identical), rabbit RHOV (99% identical), mouse Rhov (99% identical), macaque RHOV (99% identical), dog RHOV (98% identical), rat Rhov (98% identical), guinea pig RHOV (97% identical), pig RHOV (97% identical), tropical clawed frog rhov (70% identical), zebrafish rhov (58% identical). Paralogues in human: RHOU (58% identical), RAC3 (43% identical), CDC42 (43% identical), RAC2 (42% identical), RAC1 (42% identical), RHOQ (42% identical), RHOJ (40% identical), RHOG (38% identical), RHOA (34% identical), RHOB (34% identical), RHOC (33% identical), RHOD (33% identical), and 10 more.
Diseases named in the same sentence as RHOV in open-access papers:
RHOV is named in the same sentence as 50 diseases in open-access papers, as found by Europe PMC text mining. Sharing a sentence is not in itself a finding about the gene and the disease. The quoted sentences say what the papers report.
lung carcinoma (13 papers, 2017 to 2025). "The RHOV gene encodes a protein that may play a crucial role in the development and metastasis of lung cancer." (PMID 37664112, 2023). "RhoV is oncogenic in lung cancer and triple-negative breast cancer; however, in PCa, higher RhoV expression is associated with a favorable prognosis." (PMID 41301045, 2025). "Among these, RHOV was found to accumulate in lung epithelial cells as pseudo time progressed, and its downregulation attenuated lung cancer progression in vitro." (PMID 40486872, 2025). "The results showed that RHOV is significantly overexpressed in human lung cancer cell lines and after inhibiting RHOV expression, the proliferation and migration capacity of tumor cells decreased." (PMID 37234773, 2023). "RHOV is expressed in lung cancer cell lines and is upregulated in most of the lung tumor cases studied." (PMID 36186485, 2022). "A link to lung cancer was furthermore suggested in a study on non-small-cell lung cancer tumors in which the RHOV transcript was reported to be overexpressed in cell lines and in patient material." (PMID 35454871, 2022). "RHOV is highly expressed in many lung cancer cell lines and promotes the growth and metastasis of LUAD cells." (PMID 36147484, 2022). "Although RHOV expression was shown to be upregulated in lung carcinoma 10, the biological function of RHOV in cancer is unclear." (PMID 34326698, 2021). "Through a series of in vitro and in vivo experiments, we testified the correlation of RhoV and lung cancer cell progression or tumorigenesis." (PMID 33767988, 2021). "Moreover, ectopic expression of RHOV in the A549 lung cancer cell line resulted in increased wound closure and focus formation." (PMID 35454871, 2022). "Meanwhile, RhoV also was investigated that exhibits high expression in many lung cancer cell lines." (PMID 33767988, 2021). "Our study indicated that RhoV could be a tumor activator and a potential target for the treatment of human lung cancer." (PMID 33767988, 2021). "Together, these studies have suggested a role for RHOV in lung cancer, but how RHOV functionally contributes to cancer progression is not known at present." (PMID 35454871, 2022). "Moreover, knockdown RhoV promoted the sensitivity of EGFR-TKI in the gefitinib resistant PC9 cells (PC9-GR) and aggravated gefitinib-induced lung cancer cell apoptosis both in PC9 and PC9-GR cells." (PMID 33767988, 2021). "This seems that RhoV in different lung cancer types displayed different functions (data not shown), which should be further researched." (PMID 33767988, 2021). "Although RHOV has been identified to play an oncogenic role in lung cancer and triple‐negative breast cancer, its role in other types of tumors remains unknown." (PMID 37596964, 2023).
lung adenocarcinoma (12 papers, 2021 to 2026). A carcinoma that arises from the lung and is characterized by the presence of malignant glandular epithelial cells. "RHOV has been identified as one of the most up-regulated Rho GTPase members in lung adenocarcinoma and was associated with unfavorable survival by bulk and single RNA sequencing." (PMID 39478862, 2024). "RhoV was identified as one of the most significantly overexpressed Rho GTPases in lung adenocarcinoma and associated with patients’ survival." (PMID 33767988, 2021). "This study confirms that high expression of RHOV is an independent predictor of poor prognosis in lung adenocarcinoma patients, consistent with previous analyses in lung adenocarcinoma." (PMID 40672941, 2025). "Plasma EVs from lung adenocarcinoma (LUAD) are observed to consistently have higher levels of Ras Homolog Family Member V (RHOV)." (PMID 38311623, 2024). "Another study, which also analyzed expression levels of all 20 of the RHO members, concluded that RHOV was specifically overexpressed in lung adenocarcinoma." (PMID 35454871, 2022). "Elevated expression of RHOV has been shown in lung adenocarcinoma and correlated with high frequency of metastasis." (PMID 35454871, 2022). "We next investigated the critical role of RhoV in different lung adenocarcinoma cells and animal models." (PMID 33767988, 2021). "Meanwhile, we investigated the critical roles of RhoV on the growth and metastasis of different lung adenocarcinoma cells." (PMID 33767988, 2021). "RhoV was identified as one of the most significantly overexpressed Rho GTPases in lung adenocarcinoma." (PMID 33767988, 2021). "In this study, we found that RhoV was identified as one of the most significantly overexpressed Rho GTPases in lung adenocarcinoma." (PMID 33767988, 2021). "Silencing RhoV expression inhibits proliferation, migration and invasion, and tumorigenicity capacities of lung adenocarcinoma cells." (PMID 33767988, 2021). "Due to its susceptibility to ZIKV infection and rapid cytopathic effects, we chose A549, a human lung adenocarcinoma cell line, to validate the proviral phenotype of RhoV and WWTR1." (PMID 34834920, 2021). "Additionally, they identified Ras Homolog Family Member V (RHOV) to be consistently elevated in lung adenocarcinoma (LUAD) plasma EVs." (PMID 34572829, 2021). "For example, in lung adenocarcinoma (LUAD), RHOV expression was upregulated, high expression correlated with worse survival and less infiltrating immune cells, indicting RHOV as an oncogene." (PMID 37596964, 2023). "Overexpression of RhoV in lung adenocarcinoma promotes the progression and EGFR-TKI resistance, suggesting RhoV is a promising prognosis and therapeutic target of lung adenocarcinoma." (PMID 33767988, 2021). "Employing 117 machine learning algorithm combinations, we develop a robust five-gene prognostic signature (FAM83A, RHOV, CPS1, STRIP2, SLC2A1) for lung adenocarcinoma (LUAD) with area under the curve values of 0.692, 0.688, and 0.614 for 1-, 3-, and 5-year overall survival, respectively." (PMID 42062606, 2026). "Finally, seven copper death genes related to lung adenocarcinoma were screened out, including ARHGEF39, EFCC1, SERPIND1, INSL4, ANLN, RHOV and CCL20." (PMID 36313444, 2022). "Our data also indicated that RhoV induced progression and EGFR-TKI resistance of lung adenocarcinoma may be related to the activation of the AKT/ERK pathway." (PMID 33767988, 2021). "Given that LCAL1 and RHOV have been previously reported as prognostic genes, we validated the novel prognostic gene MARCHF4 via qRT-PCR, demonstrating that its expression was significantly upregulated in lung adenocarcinoma cells compared to normal lung epithelial cells." (PMID 40672941, 2025).
lymph node metastasis (2 papers, 2021 to 2024). "RHOV is overexpressed in LUAD patients, and high RHOV expression correlates with large tumor size, advanced clinical stage, lymph node metastasis, and shorter OS." (PMID 34326698, 2021). "Next, we proceeded to explore the relationship between the expression of RHOV, ANLN, PTTG1, DLGAP5, and FAM83A with pathological stage and lymph node metastasis, and the results showed that the transcriptional expression of the five prognostic features progressively increased with the stage." (PMID 39144144, 2024).
prostate carcinoma (2 papers, 2022 to 2023). A carcinoma that arises from epithelial cells of the prostate gland. "A previous study showed that RHOV was associated with tumor growth in prostate cancer." (PMID 35582196, 2022).
acute myeloid leukemia (1 paper, 2023). Acute myeloid leukemia (AML) is a group of neoplasms arising from precursor cells committed to the myeloid cell-line differentiation. "Conversely, RHOV expression was downregulated in seven tumor types: glioblastoma multiforme, kidney chromophobe, KIRC, kidney renal papillary cell carcinoma, acute myeloid leukemia, low‐grade glioma, and SKCM." (PMID 37596964, 2023).
microcephaly (1 paper, 2021). A congenital or acquired developmental disorder in which the circumference of the head is smaller than normal for the person's age and sex. "Due to ZIKV association with microcephaly and other neurological conditions, we aimed to validate the proviral phenotype of RhoV in a cell type more relevant to the central nervous system." (PMID 34834920, 2021).
virus infection (1 paper, 2021). "This enhancement of virus infection by Pak1 suggests Pak1 might participate in the same pathway that RhoV uses to support the ZIKV lifecycle in host cells." (PMID 34834920, 2021).
ZIKV infection (1 paper, 2021). "We then focused on RhoV, a Rho GTPase with atypical terminal sequences and membrane association, and validated its proviral effects on ZIKV infection and virion production in SNB-19 cells." (PMID 34834920, 2021). "This might explain why this mutation preserves the ability of RhoV to facilitate ZIKV infection." (PMID 34834920, 2021). "We also showed that the GTPase activity of RhoV plays an important role in enhancing ZIKV infection." (PMID 34834920, 2021). "We found that RhoV overexpression enhances ZIKV infection and production at multiple time points in RhoV KO A549 cell clones." (PMID 34834920, 2021). "Since we observed a significant impact on ZIKV infection and production at early timepoints in A549 cells and Rho GTPases are known to modulate viral entry, we asked if RhoV facilitates ZIKV endosomal entry." (PMID 34834920, 2021). "Further investigation identified the GTPase domain of RhoV to be critical for its proviral phenotype, while siRNA-mediated knockdown of RhoB, another Rho GTPase, and Pak1, the direct effector of RhoV, leads to reduced ZIKV infection." (PMID 34834920, 2021). "Taken together, these results highlight the positive role of RhoV in ZIKV infection and confirm CRISPR activation as a relevant method to identify novel host–pathogen interactions." (PMID 34834920, 2021). "Further studies are needed to elucidate how GTPase activity of RhoV and interactions with downstream effector proteins contribute to its proviral effects during ZIKV infection." (PMID 34834920, 2021). "If GTPase activity and interaction with downstream effector proteins are critical for ZIKV infection, we expect to see a further increase in RhoV proviral effects." (PMID 34834920, 2021). "Taken together, the GTPase activity plays an important role in the proviral function of RhoV during ZIKV infection." (PMID 34834920, 2021). "Overexpression of RhoV and WWTR1 significantly enhanced ZIKV infection by up to 2.6-fold at 12 h.p.i., an effect which persisted up to 18–24 h.p.i. for RhoV (clone 2) and WWTR1 (clone 15)." (PMID 34834920, 2021). "Overexpression of either RhoV or WWTR1 is expected to increase ZIKV infection or ZIKV-induced cell death." (PMID 34834920, 2021). "To determine which domain of RhoV is essential for its proviral effects on ZIKV infection, we generated several RhoV mutants that are mechanistically informative." (PMID 34834920, 2021). "We confirmed that RhoV enhances ZIKV infection in SNB-19 cells, a human glioblastoma cell line relevant for ZIKV tropism, at the step of entry." (PMID 34834920, 2021). "Since RhoV is an atypical Rho GTPase that is targeted to plasma membrane through palmitoylation, we tested dominant-activated, GTPase-defective (G40V and Q89L), or mislocalized (C234S) mutants for their ability to increase ZIKV infection." (PMID 34834920, 2021). "Therefore, we asked whether other related Rho GTPases and RhoV effector proteins such as Pak1 are also able to enhance ZIKV infection." (PMID 34834920, 2021). "Therefore, we investigated whether other Rho GTPases and effector protein of RhoV, Pak1, carry similar functions as RhoV during ZIKV infection in SNB-19 cells." (PMID 34834920, 2021). "We identified Ras homolog family member V (RhoV) and WW domain-containing transcription regulator 1 (WWTR1) as proviral factors, and found them to play important roles during early ZIKV infection in A549 cells." (PMID 34834920, 2021). "In this study, we identified RhoV and WWTR1 as candidate host proviral factors for ZIKV infection by performing a genome-wide CRISPR activation screen, which has the advantage of upregulating all gene isoforms from their endogenous promoter contexts." (PMID 34834920, 2021). "To investigate the effects of RhoV and WWTR1 on ZIKV infection, we treated these inducible cell lines with Dox and infected them with ZIKV." (PMID 34834920, 2021).
ZIKV infection (continued). "Although 1 μg/mL Dox induces the highest saturating level of RhoV protein, we found that Dox amounts greater than 1 μg/mL enhances ZIKV infection non-specifically in unmodified SNB-19 cells." (PMID 34834920, 2021). "Interestingly, despite the dramatic increase in virus yield in cells overexpressing RhoV at early time points that diminishes at late time points, RhoV does not appear essential for ZIKV infection." (PMID 34834920, 2021).
tumor (15 papers, 2021 to 2026). "RHOV expression showed varied associations with different types of tumor‐infiltrating immune cells and demonstrated a potential impact on the response to immunotherapy depending on the cancer type." (PMID 37596964, 2023). "The association between RHOV expression and prognosis varied across different tumor types." (PMID 37596964, 2023). "In addition, FCER2, CD200R1, and RHOV in the signature were strongly associated with the clinical stage of the tumor, and univariate cox analysis showed that except for TNNT2, WT1 and KRTAP5-8, the remaining signature genes were closely correlated with the prognosis of LUAD patients." (PMID 37234773, 2023). "Subsequently, utilizing machine learning techniques, we constructed the PIS model, comprising marker genes of CKS1B+ tumours (RHOV, ANLN, DEAR, PSMB7, KRT8, LDHA)." (PMID 38946232, 2024). "RHOV expression was identified as an independent prognostic factor in 7 of 33 types of tumors; however, the relationship varied according to tumor type." (PMID 37596964, 2023). "The univariate Cox regression analyses showed that RHOV expression was significantly correlated with OS in seven tumor types: ACC, KIRC, LUAD, PAAD, PRAD, SKCM, and UVM." (PMID 37596964, 2023). "This study provides valuable insights into the role of RHOV in pan‐cancer development, indicating its role as a tumor suppressor or oncogene according to the cancer type and tumor microenvironment." (PMID 37596964, 2023). "The results revealed that RHOV expression was upregulated in 18 tumor types and downregulated in seven tumor types." (PMID 37596964, 2023). "RHOV mRNA expression was also increased in those with advanced clinical stage, lymph node metastasis, and large tumor size." (PMID 34326698, 2021). "Taken together, these data suggests that RHOV knockdown inhibits tumor growth and metastasis of LUAD in vivo." (PMID 34326698, 2021). "In addition, we explored the relationship between TRP-related prognostic features and TME and revealed strong correlations between ANLN, DLGAP5, FAM83A, PTTG1, and RHOV with tumor immune infiltration, immune checkpoints, and substance metabolism pathways." (PMID 39144144, 2024). "First, although we observed different prognostic roles for RHOV in different cancers, we were unable to provide experimental evidence to confirm whether RHOV acts as an oncogene or a tumor suppressor in specific cancer types." (PMID 37596964, 2023). "However, in kidney renal clear cell carcinoma (KIRC), RHOV expression was downregulated, high expression correlated with better survival and more infiltrating immune cells, indicting RHOV as a tumor suppressor." (PMID 37596964, 2023). "RHOV was shown to facilitate tumor cell growth and metastasis in LUAD." (PMID 36726580, 2023). "As RHOV promotes LUAD cell proliferation in vitro, we investigated whether RHOV modulates LUAD tumor growth in nude mice." (PMID 34326698, 2021). "Remarkably, RhoV knockdown also altered some of the suppressor’s expression in tumor progression." (PMID 33767988, 2021). "However, evidence supporting the tumor‐suppressive role of RHOV remains unavailable." (PMID 37596964, 2023). "In addition, RHOV knockdown inhibits metastasis and LUAD tumor growth of nude mice, which may be related to RHOV activation of the JNK/c-Jun signaling pathway." (PMID 37091780, 2023). "Moreover, RhoV is involved in tumor cell proliferation and EMT both in vivo and in vitro." (PMID 33767988, 2021). "Moreover, knockdown of RHOV suppresses LUAD tumor growth and metastasis in nude mice." (PMID 34326698, 2021). "Genetic suppression or deletion of RHOV impaired PDAC cell invasion, migration, clonogenic growth, and context-dependent sphere formation in vitro, while reducing tumor-initiating capacity and metastatic colonization in vivo." (PMID 42098069, 2026). "The results showed that TPX2, RHOV and FAM83A expression was significantly upregulated in the tumor cell lines." (PMID 39247599, 2024).